IL6 (interleukin 6)
Diseases named in the same sentence as IL6 in open-access papers (continued):
Sharing a sentence is not in itself a finding about the gene and the disease.
COVID-19 (continued). "Therefore, TCZ is recommended in seriously ill patients with elevated IL-6 by the Diagnosis and Treatment Protocol for COVID-19 (Trial Version 7) issued by the National Health Commission of China." (PMID 35308307, 2022). "Since the beginning of the pandemic, CRP, and IL6 levels have been used as prognostic biomarkers in COVID-19; in addition, IL6 activity has been targeted for treatment by the anti-IL-6 receptor antibody but also to guide treatment and predict response to tocilizumab." (PMID 35783606, 2022). "Cytokine storm of interleukin (IL)-2, IL-4, tumor necrosis factor-alpha (TNF-α), interferon-gamma (IFN-γ), and C-reactive protein has not been directly associated with COVID-19, whereas IL-6 and IL-10 were found to be COVID-19 severity predictors." (PMID 35054524, 2022). "An abnormally high serum level of IL-6 detected in patients with COVID-19 is an important inflammatory biomarker and could be used to predict disease severity." (PMID 36497138, 2022). "On the one hand, IL-6, as a multifunctional molecule, plays a crucial role in COVID-19-related hyperinflammation, which may lead to ME/CFS through neuroinflammation." (PMID 36189286, 2022). "IL-6 and IL-10 have been recently described as COVID-19 severity predictors." (PMID 35740951, 2022). "Moreover, it was revealed that there was a cytokine storm, including interleukin-1 (IL-1), IFN-γ, TNF-α, IL-6, and others, in patients with COVID-19." (PMID 36362417, 2022). "Furthermore, some inflammatory markers [i.e., C-reactive protein (CRP), interleukin-6 (IL-6), and ferritin] were reported as solid predictors of worse outcomes in COVID-19 positive patients." (PMID 35056135, 2022). "However, CART analysis was still able to define controls and mild COVID-19 patients, with high accuracy by an algorithm based on IL-6 concentration." (PMID 34675240, 2021). "Notably, elevated IL-6 and serum C-reactive protein (CRP) (triggered by IL-6) are markers for clinical deterioration and ventilatory support in COVID-19." (PMID 33437924, 2021). "Modeling COVID-19 progression through DBNs by cytokines’ measurements over time identified notable dependencies among clinical and biological markers, where most of them are biomarkers of inflammation, including the IL-8, IL-6, CRP, LDH, and TNF." (PMID 35054223, 2021). "They observed significant differences in white blood cell counts, C-reactive protein (CRP), and IL-6, and concluded that COVID-19 mortality may be due to a virus-related “cytokine storm”." (PMID 33467466, 2021). "However, in the Cox regression multivariable analysis the main predictors of death by COVID-19 in hospitalized patients were IL-6 (HR =6.81; 95% CI: 1.6-28.7) and MCP-1 (HR =4.61; 95% CI: 1.1-19.1)." (PMID 34539631, 2021). "Furthermore, observational and retrospective studies in COVID-19 patients have suggested the clinical efficacy of IL-6 blockade with therapeutic antibodies including tocilizumab, sarilumab, and siltuximab." (PMID 34176095, 2021). "Indeed, we found a statistically significant difference in liposomal bLf-treated COVID-19 patients regarding some blood parameters, including IL-6, D-dimers, and ferritin." (PMID 34682731, 2021). "Therefore, we established a grading system for COVID-19 by combining serum IL-6 levels and current classification criteria." (PMID 33693017, 2021). "A delay in SARS-CoV-2-RNA clearance in the upper respiratory tract during the first days of the disease, higher concentrations of anti-SARS-CoV-2 IgA, IgM, and IgG and of specific cytokines (i.e., IL-6, IL-8 and MIP-1β) at baseline were associated with COVID-19 severity." (PMID 34835384, 2021). "IL-6 in particular is one of the pathologic mechanisms for lung injury in COVID-19." (PMID 34548669, 2021). "Moreover, IL-6 levels in COVID-19 patients are largely variable, since multiple measurements of serum IL-6 levels have shown fluctuations both within the course of infection and within the same patient." (PMID 34010310, 2021).
COVID-19 (continued). "Among inflammatory markers, interleukin 6 (IL-6), interleukin 1 (IL-1), cytoskeleton-associated protein 4 (CKAP4), and galectin-9 (GAL-9 or Gal-9) had received most attention as the common links between COVID-19 and AD manifestations." (PMID 33078369, 2021). "Plasma gp96 levels correlate with IL-6 and COVID-19 severity." (PMID 34817280, 2021). "We demonstrated that severe COVID-19 was associated with elevated levels of numerous plasma mediators indicative of coagulation, endothelial activation and a broad inflammatory response including CXCL10, GM-CSF, and IL-6." (PMID 33692097, 2021). "den Begriff des Zytokinsturms bei COVID-19 in Frage, da die selbst bei schweren COVID-19-Fällen beschriebenen IL-6-Spiegel zwar deutlich erhöht sind, jedoch weit unter jenen liegen, die sonst bei Non-COVID-19-ARDS oder anderen mit einem Zytokinsturm einhergehenden Entitäten beschrieben werden." (PMID 33532003, 2021). "TNF-α, IFN-γ, IL-6, IL-8, IL-4, and IL-10 were dramatically elevated in COVID-19 patients." (PMID 34646834, 2021). "IL-6 has repeatedly been reported to be high in critically ill COVID-19 patients." (PMID 34108851, 2021). "IL-6 is also elevated in obesity and cannot be specific for COVID-19 patient conditions." (PMID 34960790, 2021). "We describe a case of KS in COVID-19 patient and postulate that Interleukin-6 (IL-6) activity and steroid-induced immunodeficiency may play a major role in KS emergence." (PMID 34930492, 2021). "As clinical deterioration in COVID-19 occurs after peak viral replication in the airways has subsided, we tested the hypothesis that IL-1β and IL-6 activity was also related to disease severity." (PMID 33319166, 2021). "In severe COVID-19 patients, serum IL-6 is significantly greater than in non COVID-19 subjects." (PMID 33927728, 2021). "Our work further supports the notion that IL-6 signaling pathways could be therapeutic targets to treat COVID-19." (PMID 33390771, 2021). "The unique lipid composition of ProLungTM-budesonide has been shown to have immunomodulating effects, stabilize the endothelium, decrease IL-6 levels, and antiphospholipid antibodies, all of which may play an important role in COVID-19." (PMID 34766166, 2021). "In addition, over synthesis and persistent elevation of IL-6 can lead to a cytokine storm, which is thought to be an important manifestation of severe viral pneumonia such as influenza A pneumonia and COVID-19." (PMID 34692846, 2021). "In terms of COVID-19, data suggest that IL-6 may play a key role in the evolution of the inflammatory immune response that causes acute respiratory distress syndrome." (PMID 34872143, 2021). "The increase of macrophage-secreted IL-6 and IL-8 levels by cannabis-based treatment may potentially lead to a worsening of the "cytokine storm" identified in severe COVID-19 patients." (PMID 33446817, 2021). "The most important cytokine involved in the cytokine storm in COVID-19 is IL-6." (PMID 34689776, 2021). "The mechanism of action of baricitinib includes theoretical advantages over tocilizumab, as baricitinib decreases the concentration of several cytokines and inflammatory mediators involved in the pathogenesis of COVID-19 in addition to IL-6 and has an additional potential antiviral activity." (PMID 34820393, 2021). "Hence, tocilizumab and sarilumab were proposed as promising therapeutic strategies to reduce mortality in COVID-19, by blocking IL-6 signalling, and ameliorating the deleterious effects of the inflammatory storm." (PMID 34966381, 2021). "Moreover, we can conclude that FIB-4 reflects COVID-19 severity associated with hepatocellular damage (increased AST), systemic inflammation (increased IL-6 and ferritin), and lung damage (increased LDH), observed during acute SARS-CoV-2 infection." (PMID 34635073, 2021).
COVID-19 (continued). "In the recently published REMAP-CAP trial, a 90-day survival gain (OR 1.61, 95% credible interval 1.25 to 2.08) was seen from anti-IL-6 therapy (i.e., tocilizumab/sarilimumab) in conjunction with corticosteroids for the entire group of severe COVID-19 patients as well." (PMID 34034789, 2021). "In this study, the levels of TNF-α, IL-1α, IL-4, IL-6, IL-8, and IL-10, were measured through ELISA in sera from healthy volunteers as a control group, patients with moderate COVID-19, patients with severe COVID-19, and patients who had recovered from COVID-19." (PMID 33914789, 2021). "Evidence has shown a potential association of MCs with COVID-19, and the activation of MCs located in the submucosa of the respiratory tract by SARS-CoV-2 is known to lead to the release of pro-inflammatory cytokines such as IL-1, IL-6 and TNF-α." (PMID 34359931, 2021). "Therefore, amygdalin is a candidate compound for COVID-19 treatment by regulating IL6, SRC, MAPK1, MAPK3, VEGFA and EGFR." (PMID 34908920, 2021). "However, together these data suggest that the contribution of IL-6 and IL-1B to cytokine storm in severe COVID-19 is the result of systemic immune dysregulation downstream of the epithelium." (PMID 34867390, 2021). "Previously performed but rather small in sample number and not placebo-controlled studies suggested the beneficial effect of leronlimab induced decrease of IL-6 levels in severe COVID-19: Over the two-week study period 6/10 patients survived, two were extubated, and one patient was discharged." (PMID 33445810, 2021). "Thus, WS can be considered for the investigation to mitigate cytokine storm in patients with COVID-19, with special reference to IL-1β and IL-6." (PMID 34012390, 2021). "Therefore, extraordinary circulating IL-6 is deemed to be the possible link AKI with ARDS in COVID-19." (PMID 34629845, 2021). "IL-6 is elevated during the cytokine storm in COVID-19 patients." (PMID 34033878, 2021). "Interestingly, a recent in-depth meta-analysis of 1302 COVID-19 cases showed that the level of IL-6 was 3-fold higher in patients with severe vs mild/moderate COVID-19 (p < 0.001)." (PMID 33465050, 2021). "Furthermore, a small retrospective observational study conducted in China suggests the efficacy of tocilizumab (an IL-6 inhibitor) in the treatment of 21 COVID-19 patients with severe pneumonia and high IL-6." (PMID 33495742, 2021). "Besides, previous studies demonstrated that interleukin-2R (IL-2R)/lymphocyte, interleukin-6 (IL-6) and interleukin-10 (IL-10) might be the potential biomarkers for early diagnosis and indicators for higher risk of disease deterioration when predicting the disease progression of COVID-19." (PMID 34282057, 2021). "To find an alternative disease timer, we compared the testing frequency of routine laboratory parameters such as the acute phase inflammatory marker CRP, the inflammatory cytokine interleukin 6 (IL-6), myoglobin and cardiac troponin that have previously been correlated to COVID-19 severity." (PMID 34307391, 2021). "In the context of severe acute respiratory syndrome coronavirus 2 (SARS-CoV-2) infections, IL-6 is thought to be involved in the cytokine storm following infection and treatment of patients with IL-6 inhibitors is currently under review." (PMID 34293057, 2021). "High IL-6 levels are reported in COVID-19 related deaths in China." (PMID 33673818, 2021). "Given that IL-6 is one of the key cytokines that are correlated with disease progression and severity, IL-6 inhibitors may be of benefit to patients with severe COVID-19." (PMID 33445583, 2021). "Interestingly, macrophages infected with SARS-CoV-2 and isolated postmortem from lymph nodes and spleens of COVID-19 patients have shown high levels of IL-6 expression." (PMID 33467724, 2021).
COVID-19 (continued). "Otherwise, in the acute phase of COVID-19, a storm of plasma cytokines and chemokines has been described, with higher markers of inflammation (e.g. C-reactive protein, ferritin, IL-2 IL-4, IL-6, IL-8, IL-10, TNF-α, and INF-γ) in patients with more severe presentations." (PMID 33890193, 2021). "Further studies investigating the potential therapeutic effect of specific anti-inflammatories, such as anti-IL-6 antibodies, anti-diabetic drugs or, perhaps, anti-coagulant drugs, in COVID-19 treatment of patients with obesity or MS may be crucial." (PMID 33809913, 2021). "Rather, flow cytometry of immune cells from patients with COVID-19 showed that impaired immune cell cytotoxicity in severe cases was IL-6-dependent; thus, targeting IL-6 may restore antiviral activity." (PMID 34631752, 2021). "Our results show that both HMGB1 and IL‐6 are important biomarkers of disease severity in COVID-19 and could guide early recognition of the most severe patients at the moment of ICU admission." (PMID 33939645, 2021). "IL-6 also plays an important role in COVID-19 pathophysiology." (PMID 33741059, 2021). "In addition, increased levels of cytokines (e.g., IL-6, IL-10, and TNF-α) have been associated with severe COVID-19." (PMID 34484133, 2021). "On the other hand, it is of interest, that, some of the main drugs used in patients hospitalized with COVID-19 (like corticosteroids, IL6 inhibitors, Jak inhibitors etc.)are immunosuppressive/immunomodulatory drugs commonly used in autoimmune/autoinflammatory diseases." (PMID 34512643, 2021). "However, laboratory parameters associated with COVID-19 such as CRP, IL-6, and BUN were also used in a few studies." (PMID 34367265, 2021). "Interestingly, Mann and colleagues observed an early rise of IL-6 level in critically ill patients of COVID-19, which progressively decreased over time even if the patient did not survive." (PMID 34775962, 2021). "Emerging evidence indicates that high levels of IL-6 are observed in COVID-19 patients." (PMID 33146673, 2021). "Interestingly, IL-6 is a major cytokine released during the “cytokine storm”, the main responsible for COVID-19 complications, primarily represented by the development of acute respiratory distress syndrome (ARDS)." (PMID 34179542, 2021). "Among the core host factors that determine COVID-19 susceptibility and early disease progression, angiotensin-converting enzyme 2 (ACE2) and interleukin (IL)-6 were focused upon because of their critical roles directly involved in viral infection and host immunopathies." (PMID 33503821, 2021). "In addition to this, patients with severe COVID-19 who received mechanical ventilation showed increased levels of IL-6." (PMID 34439868, 2021). "Most COVID-19 patients exhibit increased circulating levels of IL-6, IL-1b, and TNF, as well as IL-2, IL-8, reflecting the disease severity, which results in massive systemic immunosuppression and in lymphopenia and neutrophilia, two key hematological features of COVID-19." (PMID 33815868, 2021). "This study suggests that TCZ may help to improve the prognosis of patients with COVID-19 with the baseline IL-6 level below the cutoff value of 100 pg/ml with an acceptable safety profile." (PMID 33937333, 2021). "The increased IL-6 levels are found in more than half of COVID-19 patients." (PMID 34063964, 2021). "Moreover, TT, CRP, LDH, leukocytes, ferritin and IL-6 would be related not only with COVID-19 severity but also with mortality, in the same way as lymphocytes and TGF-β." (PMID 34439469, 2021). "Moreover, a significant increase in the populations of CD14+ and CD16+ monocytes producing IL-6 was also validated in the peripheral blood samples of patients with COVID-19 through scRNA-seq analysis of peripheral blood mononuclear cells." (PMID 33777844, 2021). "Yu and colleagues reported that HCQ treatment could reduce serum interleukin-6 (IL-6) levels in COVID-19 patients." (PMID 34384388, 2021).
COVID-19 (continued). "Additionally, they noted that median IL-6 levels are 10- to 200-fold greater in patients with the hyperinflammatory phenotype of ARDS than in individuals with severe COVID-19." (PMID 34945111, 2021). "Viral load with raised IL-6 levels in critically ill COVID-19 patients is worth observing." (PMID 35110105, 2021). "Regarding a hypothetical relationship of FGF-21 with the severity of COVID-19 course in our study, we could discern significantly positive correlation in this hepatokine levels and such inflammation markers as ferritin or IL-6." (PMID 34680053, 2021). "Considering tocilizumab preventing IL-6 itself from binding to its receptor and alleviating the inflammatory responses 1, we explored the changes of inflammatory hallmarks in tocilizumab users with severe/critical COVID-19." (PMID 34131411, 2021). "Increased IL-6 levels also contribute to acute lung injury in murine models, similar to those observed in patients with severe acute respiratory syndrome in COVID-19; thus, inhibition of enhanced IL-6 level seems to mitigate acute lung injury." (PMID 34248612, 2021). "It was proposed that IL-6 might be a potential biomarker in predicting clinical outcome in critically ill COVID-19 patients." (PMID 34123873, 2021). "The significantly reduced Th and Tc cells and significantly increased IL-6, IL-10, ferritin, procalcitonin, and SAA at this stage in children with critical COVID-19 may be closely associated with the systemic cytokine storm caused by immune dysregulation." (PMID 33865340, 2021). "Itolizumab reduced circulating IL-6 concentrations in the three COVID-19 patients." (PMID 33397150, 2021). "Furthermore, a cytokine analysis study of 131 plasma specimens demonstrated that plasma concentrations of several cytokines, including IFN-α, IFN-γ, IL-6, IL-8, and IL-10, were significantly increased in severe cases of COVID-19 compared to control groups." (PMID 34901061, 2021). "Chloroquine inhibits the production and release of tumor necrosis factor (TNF) and interleukin-6 (IL-6), suggesting that it could suppress the cytokine storm in COVID-19 patients." (PMID 34099015, 2021). "Serum levels of IL-4, IL-10, IL-6 and IL1β were elevated in COVID-19 patients." (PMID 34942956, 2021). "IL-6 may play a key role in driving the COVID-19 hyper-inflammation, so blockade of IL-6 signaling is promising to improve survival efficiency." (PMID 33664741, 2021). "Moreover, COVID-19 patients experience major lung damage (due to viral replication) and immune dysregulation, which is modulated by the use of corticosteroids, anti–IL-6 monoclonal antibodies (tocilizumab, sarilumab), or other immunomodulatory agents." (PMID 34356931, 2021). "Other cytokines like IL-1β and IL-6, which have been linked to COVID-19 severity and the ensuing cytokine storm, did not exhibit comparable increases in pulmonary neutrophils and did not elicit IL-8 release from blood neutrophils in vitro." (PMID 34403366, 2021). "In contrast, trials in animal models with IL6 deficiency showed an association of this deficiency and a predisposition to CAPA, and thus, both IL6 receptor antagonist and antifungal are considered as prophylaxis in severe COVID-19 patients." (PMID 34575758, 2021). "The predictive factors which could predispose to a more severe course of COVID-19, including the presence of pneumonia and ICU hospitalization, were GGT activity, IL-6, and CRP." (PMID 34728695, 2021). "Thus far, this COVID-19-associated CS has predominantly been characterized by the presence of IL-1β, IL-2, IL-17, IL-8, TNF, CCL2, and most notably IL-6." (PMID 33443016, 2021). "In this study, 44 potential targets were obtained through the intersection of the disease targets of COVID-19 and the action targets of AE, which are mainly related to inflammatory or immune factors, such as IL-6, MAPK1, MAPK8, IL1B, RELA, CXCL-8, CCL2, and PTGS2." (PMID 33658066, 2021).